TBC1D7 (TBC1 domain family member 7)
Description:
Non-catalytic component of the TSC-TBC complex, a multiprotein complex that acts as a negative regulator of the canonical mTORC1 complex, an evolutionarily conserved central nutrient sensor that stimulates anabolic reactions and macromolecule biosynthesis to promote cellular biomass generation and growth. The TSC-TBC complex acts as a GTPase-activating protein (GAP) for the small GTPase RHEB, a direct activator of the protein kinase activity of mTORC1. In absence of nutrients, the TSC-TBC complex inhibits mTORC1, thereby preventing phosphorylation of ribosomal protein S6 kinase (RPS6KB1 and RPS6KB2) and EIF4EBP1 (4E-BP1) by the mTORC1 signaling. The TSC-TBC complex is inactivated in response to nutrients, relieving inhibition of mTORC1.
Synonyms: TBC7; dJ257A7.3; FLJ32666; MGCPH; PIG51; TBC1D7-LOC100130357
Tractability: PROTAC: ubiquitination databases record sites on it; its protein half-life has been measured.
Gene: Protein-coding gene on chromosome 6 (13,266,542 to 13,328,583, reverse strand). Ensembl gene ENSG00000145979.
Subcellular location: Lysosome membrane; Cytoplasmic vesicle; Cytoplasm, cytosol
Pathways (Reactome):
Vesicle-mediated transport: TBC/RABGAPs
Gene Ontology:
Molecular function: GTPase activator activity; protein binding; small GTPase binding; TSC1-TSC2 complex binding
Biological process: activation of GTPase activity; cellular response to starvation; negative regulation of cilium assembly; negative regulation of TOR signaling; negative regulation of TORC1 signaling; positive regulation of GTPase activity; positive regulation of protein ubiquitination; response to growth factor
Cellular component: ciliary basal body; cytoplasmic vesicle; cytosol; lysosomal membrane; TSC1-TSC2 complex
Genetic constraint (gnomAD): Loss-of-function variants: 29 observed, 27.63 expected, observed/expected ratio (o/e) 1.05, 90% interval 0.78 to 1.43. The upper end of that interval is the gene's LOEUF score, 1.43, which puts it in group 5 of 6, group 1 being the genes least tolerant of losing a copy. Missense variants: 319 observed, 323.83 expected, observed/expected ratio (o/e) 0.99, 90% interval 0.9 to 1.08. Synonymous variants: 116 observed, 117.24 expected, observed/expected ratio (o/e) 0.99, 90% interval 0.85 to 1.15.
Homologues: Orthologues: chimpanzee TBC1D7 (99% identical), macaque TBC1D7 (98% identical), dog TBC1D7 (93% identical), rabbit TBC1D7 (92% identical), rat Tbc1d7 (91% identical), mouse Tbc1d7 (91% identical), pig TBC1D7 (91% identical), guinea pig TBC1D7 (90% identical), zebrafish tbc1d7 (67% identical), Drosophila melanogaster TBC1d7 (32% identical).
Diseases named in the same sentence as TBC1D7 in open-access papers:
TBC1D7 is named in the same sentence as 17 diseases in open-access papers, as found by Europe PMC text mining. Sharing a sentence is not in itself a finding about the gene and the disease. The quoted sentences say what the papers report.
tuberous sclerosis (5 papers, 2021 to 2025). Hereditary disease characterized by seizures, intellectual disability, developmental delay, and skin and ocular lesions. "Over the past three decades the proteins Tuberin, Hamartin and TBC1D7 have emerged as a large protein complex called the Tuberous Sclerosis Complex." (PMID 35096832, 2021). "Mutations in the TBC1D7 gene do not cause tuberous sclerosis complex, but its deficiency can lead to symptoms linked to mTOR abnormalities, like intellectual disability and megalocephaly." (PMID 39901197, 2025). "Mutations in TSC1 or TSC2 cause tuberous sclerosis complex, but no germline mutations in TBC1D7 have been found in patients." (PMID 39901197, 2025). "The tuberous sclerosis complex, comprised of TSC1, TSC2 and TBC1D7 components, negatively regulates mTORC1 through Rheb GAP activity." (PMID 38746323, 2024). "DDIT4 positively regulates the activity of the Tuberous Sclerosis (TSC) complex (TSC1, TSC2 and TBC1D7), which in turn acts as a crucial negative regulator for the mTORC1 activity." (PMID 36674750, 2023).
melanoma (4 papers, 2020 to 2024). A malignant, usually aggressive tumor composed of atypical, neoplastic melanocytes. "TBC1D7 deficiency induced by siRNA suppressed the proliferation of melanoma cells A375 and Sk-Mel-28 obviously." (PMID 33194704, 2020). "Using cultured melanoma cells, (primary and metastatic melanoma cell lines derived from the same patient), the authors highlighted that TBC1D7 increases cell invasion by influencing the activity of MMP2 and MMP9." (PMID 36143291, 2022). "In our study, we also observed that interference of TBC1D7 expression inhibited the proliferation, migration and invasion of melanoma cells A375 and Sk-Mel-28 in vitro, suggesting the potential role of TBC1D7 in melanoma." (PMID 33194704, 2020). "Collectively, these results suggested that TBC1D7 inhibits the migration and invasion ability of melanoma cells." (PMID 33194704, 2020). "Seven prognosis associated TBCs genes including TBC1D13, TBC1D16, TBC1D7, TBC1D10C, TBC1D19, TBC1D8B, and TBC1D15 were identified in melanoma." (PMID 33194704, 2020). "What’s more, Interference of TBC1D7 was confirmed to inhibit the migration and invasion in melanoma cells in vitro, indicating the potential therapeutic role of TBC proteins in melanoma." (PMID 33194704, 2020). "The results showed that depletion of TBC1D7 in both melanoma cell lines A375 and Sk-Mel-28 impeded the ability of migration." (PMID 33194704, 2020). "What’s more, interference of one of the seven TBC proteins TBC1D7 was confirmed to inhibit the proliferation, migration and invasion of melanoma cells in vitro." (PMID 33194704, 2020). "In order to further investigate the function role of TBC proteins in melanoma, TBC1D7, one of TBC proteins was chosen for subsequent functional validation." (PMID 33194704, 2020). "TBC1D7 has also been shown to promote melanoma cell invasion and melanoma metastasis." (PMID 38766486, 2024). "TBC1D7 mRNA expression in both melanoma cell lines A375 and Sk-Mel-28 were successfully interfered with siRNA which was confirmed by RT-PCR, and two sequences of them were selected to explore the effect of TBC1D7 on melanoma cells." (PMID 33194704, 2020). "However, more experiments needed to be performed to investigate the detailed mechanism of TBC1D7 in melanoma cells, and the biological function of the seven prognostic-associated TBCs in melanoma is still largely unknown, further study should be clarified the effect of TBCs on melanoma." (PMID 33194704, 2020). "Similarly, suppression of TBC1D7 with siRNA also inhibited the invasion of melanoma cells remarkably." (PMID 33194704, 2020).
lung carcinoma (3 papers, 2020 to 2024). "RNAi interference of TBC1D7 in lung cancer cells inhibited cell growth; conversely, overexpression of TBC1D7 promoted lung cancer cell proliferation and promoted tumor formation in mice." (PMID 35918393, 2022). "High TBC1D7 levels have been observed in several lung cancers and have been correlated with poor patient outcomes." (PMID 35918393, 2022). "TBC1D7, the GAP for Rab17, can significantly promote the growth of lung cancer cells, and an obvious correlation between the expression of TBC1D7 and poor prognosis is observed." (PMID 33194704, 2020). "Highly expression of TBC1D7 was related with poor outcome in non-small cell lung cancer (NSCLC), and suppression of TBC1D7 inhibits the growth of lung cancer cells, which might be a promising target in cancer therapy." (PMID 33194704, 2020). "The high expression of TBC1D7, a GAP for Rab17, was found in lung cancer tissues, which can significantly drive the development of lung cancer cells and was correlated with poor prognosis of patients." (PMID 39439452, 2024).
Intellectual disability (2 papers, 2014 to 2020). "Although no TBC1D7 mutations have yet been found in TSC patients, homozygous loss of TBC1D7 causes intellectual disability, megaencephaly and increased TORC1 signalling." (PMID 24714658, 2014). "It has been reported that TBC1D7 is related with various diseases such as intellectual disability, megalencephaly, diabetes and tumor." (PMID 33194704, 2020).
colorectal cancer (1 paper, 2023). A primary or metastatic malignant neoplasm that affects the colon or rectum. "Knowing that RUNX3 represses TBC1D7, our observation appears to pinpoint RUNX3 to reciprocal control of the Wnt/β-catenin and PI3K/AKT/mTORC1 pathways, inter alia involved in the failure of colorectal cancer treatment." (PMID 37371794, 2023).
migraine (1 paper, 2016). "An eQTL for TBC1D7 has been significantly associated with migraine and migraine without aura in a study of 23,285 individuals with migraine and 95,425 population-matched controls." (PMID 27499730, 2016).
prostate carcinoma (1 paper, 2020). A carcinoma that arises from epithelial cells of the prostate gland. "In prostate cancer, the frequency of TSC1 and TBC1D7 mutation or deep deletion is low (≤0.8% incidence), whereas TSC2 mutation and deep deletion are more frequent (1–1.8% and up to 4.2% of cases respectively)." (PMID 32630372, 2020). "Remarkably, up to 3%, 4%, and 7% of patients with prostate cancer also display TBC1D7, TSC1, and TSC2 high-level amplification respectively, yet the functional consequence is currently unclear." (PMID 32630372, 2020).
Tics (1 paper, 2025). Repeated, individually recognizable, intermittent movements or movement fragments that are almost always briefly suppressible and are usually associated with awareness of an urge to perform the movement. "Additionally, genes such as TBC1D7 further complicate the relationship between ADHD and tics." (PMID 39752340, 2025).
tumor (6 papers, 2016 to 2024). "The TSC gene products TSC2 and TSC1 are tumor suppressors that form a complex with TBC1 domain family member 7 (TBC1D7)." (PMID 36835331, 2023). "A xenograft tumor model was established to further explore the role of the TBC1D7 and KIF2C interaction in tumor growth." (PMID 32748349, 2021). "In the present study, the expression of TBC1D7 in HCC tissues was higher than in normal tissues, and TBC1D7 expression was significantly correlated with cancer stage and tumor grade." (PMID 38766486, 2024). "The ectopic expression of TBC1D7 was shown to reduce KIF2C-increased tumor volume and tumor weight." (PMID 32748349, 2021).
cancer (3 papers, 2020 to 2024). A tumor composed of atypical neoplastic, often pleomorphic cells that invade other tissues. "The results showed that the mRNA levels of TBC1D1, TBC1D7, TBC1D8 and TBC1D14 significantly varied between different cancer stages, whereas the mRNA levels of TBC1D9b and TBC1D25 did not." (PMID 38766486, 2024).
neurodevelopmental disorder (1 paper, 2025). A behavioral and cognitive disorder with onset during the developmental period that involves impaired or aberrant development of intellectual, motor, or social functions. "A further patient was identified in a study of patients with undiagnosed neurodevelopmental disorders who had compound heterozygous variants in TBC1D7, again consistent with a loss-of-function disease mechanism." (PMID 40426219, 2025).
TBC1D7 also shares sentences with these, for which no sentence is quoted: breast carcinoma (1 paper); diabetes (1); epilepsy (1); Macrocephaly (1); megalencephaly (1); skin cutaneous melanoma (1).